RN7SL741P (RNA, 7SL, cytoplasmic 741, pseudogene)
Gene: Miscellaneous RNA gene on chromosome 13 (25,944,478 to 25,944,766, forward strand). Ensembl gene ENSG00000242381.
Homologues: Orthologues: chimpanzee Metazoa_SRP (82% identical), macaque Metazoa_SRP (81% identical). Paralogues in human: RN7SL2 (74% identical), RN7SL1 (74% identical), RN7SL126P (74% identical), RN7SL743P (74% identical), RN7SL3 (73% identical), RN7SL45P (73% identical), RN7SL679P (73% identical), RN7SL786P (73% identical), RN7SL230P (73% identical), RN7SL357P (73% identical), RN7SL478P (73% identical), RN7SL551P (73% identical), and 706 more.